NONO (non-POU domain containing octamer binding)
Description:
DNA- and RNA binding protein, involved in several nuclear processes. Binds the conventional octamer sequence in double-stranded DNA. Also binds single-stranded DNA and RNA at a site independent of the duplex site. Involved in pre-mRNA splicing, probably as a heterodimer with SFPQ. Interacts with U5 snRNA, probably by binding to a purine-rich sequence located on the 3' side of U5 snRNA stem 1b. Together with PSPC1, required for the formation of nuclear paraspeckles. The SFPQ-NONO heteromer associated with MATR3 may play a role in nuclear retention of defective RNAs. The SFPQ-NONO heteromer may be involved in DNA unwinding by modulating the function of topoisomerase I/TOP1. The SFPQ-NONO heteromer may be involved in DNA non-homologous end joining (NHEJ) required for double-strand break repair and V(D)J recombination and may stabilize paired DNA ends. In vitro, the complex strongly stimulates DNA end joining, binds directly to the DNA substrates and cooperates with the Ku70/G22P1-Ku80/XRCC5 (Ku) dimer to establish a functional preligation complex. NONO is involved in transcriptional regulation. The SFPQ-NONO-NR5A1 complex binds to the CYP17 promoter and regulates basal and cAMP-dependent transcriptional activity. NONO binds to an enhancer element in long terminal repeats of endogenous intracisternal A particles (IAPs) and activates transcription (By similarity). Regulates the circadian clock by repressing the transcriptional activator activity of the CLOCK-BMAL1 heterodimer (By similarity). Important for the functional organization of GABAergic synapses (By similarity). Plays a specific and important role in the regulation of synaptic RNAs and GPHN/gephyrin scaffold structure, through the regulation of GABRA2 transcript (By similarity). Plays a key role during neuronal differentiation by recruiting TET1 to genomic loci and thereby regulating 5-hydroxymethylcytosine levels (By similarity). Plays a role in the regulation of DNA virus-mediated innate immune response by assembling into the HDP-RNP complex, a complex that serves as a platform for IRF3 phosphorylation and subsequent innate immune response activation through the cGAS-STING pathway. Promotes activation of the cGAS-STING pathway in response to HIV-2 infection: acts by interacting with HIV-2 Capsid protein p24, thereby promoting detection of viral DNA by CGAS, leading to CGAS-mediated inmmune activation. In contrast, the weak interaction with HIV-1 Capsid protein p24 does not allow activation of the cGAS-STING pathway.
Synonyms: p54(nrb); p54nrb; NMT55; NRB54; P54; PPP1R114; MRXS34
Tractability: Small molecule: a structure with a bound ligand is known. PROTAC: UniProt records ubiquitination sites on it; ubiquitination databases record sites on it; its protein half-life has been measured.
Chemical probes: (R)-SKBG-1 (high quality)
Gene: Protein-coding gene on chromosome X (71,254,270 to 71,301,522, forward strand). Ensembl gene ENSG00000147140.
Subcellular location: Nucleus; Nucleus, nucleolus; Nucleus speckle; Chromosome
Subcellular location (Human Protein Atlas): Nucleoplasm; Nucleoli; Nucleoli fibrillar center
Gene Ontology:
Molecular function: identical protein binding; protein binding; RNA binding; chromatin binding; lncRNA binding; nucleic acid binding
Biological process: activation of innate immune response; negative regulation of oxidative stress-induced neuron intrinsic apoptotic signaling pathway; circadian rhythm; mRNA processing; negative regulation of DNA-templated transcription; regulation of circadian rhythm; regulation of DNA-templated transcription; RNA splicing; cellular response to angiotensin; cellular response to hypoxia; negative regulation of apoptotic process
Cellular component: fibrillar center; membrane; nuclear matrix; nuclear speck; nucleolus; nucleoplasm; nucleus; paraspeckles; RNA polymerase II transcription regulator complex; chromosome
Gene-disease validity (ClinGen):
ClinGen rates the evidence that NONO causes each of these diseases.
X-linked syndromic intellectual disability (X-linked): Definitive.
Cancer hallmarks: proliferative signalling (promotes); change of cellular energetics (promotes); invasion and metastasis (promotes)
Homologues: Orthologues: chimpanzee NONO (100% identical), dog NONO (99% identical), pig NONO (99% identical), mouse Nono (99% identical), rat Nono (99% identical), macaque NONO (92% identical), tropical clawed frog nono (77% identical), zebrafish nono (62% identical), Drosophila melanogaster nonA (38% identical), Drosophila melanogaster nonA-l (37% identical), Drosophila melanogaster nito (12% identical). Paralogues in human: SFPQ (60% identical), PSPC1 (59% identical), SPEN (24% identical), RAVER1 (18% identical), RBM15 (16% identical), RAVER2 (15% identical), RBM15B (13% identical).
Diseases named in the same sentence as NONO in open-access papers:
NONO is named in the same sentence as 72 diseases in open-access papers, as found by Europe PMC text mining. Sharing a sentence is not in itself a finding about the gene and the disease. The quoted sentences say what the papers report.
melanoma (9 papers, 2013 to 2025). A malignant, usually aggressive tumor composed of atypical, neoplastic melanocytes. "YBX1 mediates MIA/CD-RAP-dependent p54nrb (non-POU-domain-containing octamer-binding protein) transcriptional activation, with the p54nrb promoter serving as a MIA/CD-RAP-mediated regulator implicated in chondrogenesis and malignant melanoma progression." (PMID 40799245, 2025). "Here, we report that USP11 and NONO colocalize and interact with each other in the nucleus of melanoma cells." (PMID 33369124, 2021). "We previously found that the RNA-binding protein NONO regulates the intra-S phase checkpoint and its silencing impaired HeLa and melanoma cell response to UV-induced DNA damage." (PMID 27816966, 2016). "On these bases p54nrb or the murine NonO seem to be a new molecule that function as regulator of malignant melanoma progression." (PMID 24101161, 2013). "Simvastatin completely switched off the NonO expression in B16-F10 melanoma cells, while the expression of this gene was present in untreated B16 cells." (PMID 24101161, 2013). "In our experiments 24-h treatment with simvastatin completely inhibits the expression of NonO in melanoma cells." (PMID 24101161, 2013). "This suggests that both USP11 and NONO are overexpressed in melanoma." (PMID 33369124, 2021). "On these bases the inhibited expression of NonO, in simvastatin treated cells, might suggest a possible action mechanism to explain the reduction of melanoma progression in mice administered with this drug." (PMID 24101161, 2013). "Further experimentation is required to demonstrate if NonO is a common target of statin treatment and if the downregulation is common to other cancer cells apart from B16 melanoma cells and whether this effect is dose- and time-dependent." (PMID 24101161, 2013). "NonO is involved in mRNA transcription, in splicing and consequently in protein synthesis and it may play an important role in cell proliferation and probably also in B16 melanoma progression." (PMID 24101161, 2013). "Knockdown of NONO/RALY complex components reversed YB-1 overexpression-induced oxaliplatin resistance in CRC cells, while NONO silencing modulated the cellular response to ultraviolet-induced DNA damage in melanoma cells." (PMID 33420374, 2021). "Our data suggest that either p54nrb or NonO seem to be new molecules that function as regulator of progression of malignant melanoma cells." (PMID 24101161, 2013). "Functionally, USP11 mediated melanoma cell proliferation via the regulation of NONO levels because ablation of USP11 inhibits the proliferation which could be rescued by ectopic expression of NONO protein." (PMID 33369124, 2021). "Collectively, these results demonstrate that USP11 is a new deubiquitinase of NONO and that the signalling axis of USP11‐NONO is significantly involved in melanoma proliferation." (PMID 33369124, 2021).
glioblastoma (8 papers, 2021 to 2026). The most malignant astrocytic tumor (WHO grade IV). "In glioblastoma, NONO cooperatively binds to the intron region of GPX1 pre-mRNA with PSPC1, regulating the alternative splicing of GPX1, which affects tumor growth, invasion, and redox homeostasis." (PMID 41174721, 2025). "In glioblastoma, expressions of NONO and TAZ are both upregulated and predict poor prognosis." (PMID 34716691, 2021). "Our study demonstrates that TRIM25 promotes glioblastoma cell growth and invasion by regulating the PRMT1/c-MYC pathway through mediation of the splicing factor NONO." (PMID 38303029, 2024). "This study shows that the nuclear paraspeckle protein NONO, a TAZ‐binding protein, is required for TAZ LLPS and activation in the nucleus, as well as TAZ‐driven oncogenic transcriptional program in glioblastoma tumorigenesis." (PMID 34716691, 2021). "Non-POU domain-containing octamer-binding protein (NONO), a Drosophila behavior human splicing (DBHS) protein, was found highly expressed in glioblastoma (GBM)." (PMID 37506056, 2023).
breast carcinoma (7 papers, 2016 to 2025). "BRK is a non-receptor tyrosine kinase overexpressed in approximately two-thirds of breast carcinomas as well as in some metastatic melanomas, renal carcinomas, and prostate cancers —neoplasias in which either NonO, PSF or both have been implicated [21." (PMID 27992859, 2016). "Finally, COPS5, HDAC2, and NONO were selected as hub TFs because of their significantly higher expression in breast cancer, lower survival probability in the high-risk group, and specific target genes." (PMID 34993131, 2021). "Since the expression of NONO protein was upregulated in human breast cancer tissues and its binding with PIN1 promotes its stability." (PMID 37370134, 2023). "Results of the TF–target gene network, expression panel, and survival analysis revealed that COPS5, HDAC2, and NONO served as the hub TFs for breast cancer." (PMID 34993131, 2021). "Consistent with the bioinformatics analysis, COPS5, HDAC2, and NONO were more highly expressed in breast cancer cell lines than in normal breast epithelial cells." (PMID 34993131, 2021). "Given its crucial role in regulating the Akt/MAPK/β-catenin signaling and other cellular processes, NONO might be a potential therapeutic target for breast cancer." (PMID 37370134, 2023). "COPS5, HDAC2, and NONO were recognized as hub TFs in breast cancer." (PMID 34993131, 2021). "Moreover, three hub TFs (COPS5, HDAC2, and NONO) were isolated as the prognostic biomarkers of breast cancer through the TF–target gene network, expression profile, and survival probability of the 10 prognosis-related TFs in breast cancer." (PMID 34993131, 2021). "NONO, a multifunctional nuclear RNA binding protein, is an established oncogene in neuroblastoma and can stabilize SREBP in breast cancer." (PMID 40955587, 2025). "In addition, NONO, a nuclear protein, could interact with MSN to phosphorylate CREB and upregulate downstream gene expression as well as promote the progression of breast cancer." (PMID 34993131, 2021). "We showed that PCDH19 localizes to the nuclear fraction of MCF-7 breast-cancer cells and interacts with non-POU-domain-containing octamer-binding protein (NONO)/p54nrb (a regulator of steroid hormone receptors) to coregulate oestrogen receptor (ER) α-mediated transcription." (PMID 34575929, 2021).
hepatocellular carcinoma (4 papers, 2019 to 2025). A malignant tumor that arises from hepatocytes. "A recent study emphasized the interaction between Dio3os and the NONO protein, which impedes the NONO-mediated nuclear export of ZEB1 mRNA, a crucial pathway in attenuating hepatocellular carcinoma progression." (PMID 41235096, 2025).
Intellectual disability (4 papers, 2018 to 2024). "For example, phosphosites on CDK13, TCF20 and NONO, genes that are known to be strongly associated with intellectual disability, exhibit varying temporal profiles (Sup." (PMID 39282277, 2024).
gastric cancer (3 papers, 2018 to 2025). A primary or metastatic malignant neoplasm involving the stomach. "Rescue studies indicated that circ-hnRNPU inhibited the N- and O-glycosylation, growth, invasion, and metastasis of gastric cancer cells via interacting with NONO protein." (PMID 37993881, 2023). "In these gastric cancer cases, the expression of circ-hnRNPU, NONO, or c-Myc was negatively or positively correlated with that of target genes GALNT2, GALNT6, MGAT1, or hnRNPU." (PMID 37993881, 2023). "In this study, we demonstrate that ERG serves as a crucial transcriptional regulator that promotes the expression of Ets-1, while NONO functions as a coactivator of ERG in gastric cancer." (PMID 29773901, 2018). "We believe that this study extends our knowledge about the regulation of glycosyltransferase and hnRNPU expression by circRNA and its protein partner, and suggests that circ-hnRNPU/NONO/c-Myc axis may be a potential therapeutic target for gastric cancer." (PMID 37993881, 2023). "In addition, circ-hnRNPU inhibits glycosylation, growth, invasion, and metastasis of gastric cancer cells via interacting with NONO protein, providing a therapeutic target for protein glycosylation and cancer progression." (PMID 37993881, 2023). "Similarly, gastric cancer (GC)-derived exosomal BGN is internalized by macrophages, where it interacts with NONO protein to drive pro-tumoral polarization and CXCL10 upregulation." (PMID 41417432, 2025).
multiple myeloma (3 papers, 2020 to 2024). "Since plasma cells express a high level of PRDM1 and secrete IL-6, we wanted to know whether PRDM1 and NonO regulate IL-6 in the human myeloma B cell lines, U-266, and RPMI-8226 since both cell lines express a high level of PRDM1 and NonO." (PMID 32765503, 2020). "A predictive model developed by Mohamad and others, based on five genes including CKS1B, CCT2, PRKDC, NONO, and UBE2A, successfully predicted the prognosis of patients with multiple myeloma and has been validated in several independent datasets." (PMID 39046884, 2024). "In contrast to MO-DCs, there is high level of endogenous IL-6 expression in myeloma cells which was not further increased by stimulation with LPS, and no significant induction of IL-6 when NonO levels were decreased." (PMID 32765503, 2020). "Daudi, a non-myeloma B cell line with a high level of NonO but not PRDM1, was used as a negative control." (PMID 32765503, 2020). "NonO interaction to PRDM1 regulates gene transcription in MO-DCs but not in myeloma cells, representing a new paradigm for exploring lineage specific effects of transcriptional regulators." (PMID 32765503, 2020). "Hence, in myeloma cells, NonO could be recruited to a PRDM1 complex but no PRDM1-mediated regulatory effects on IL-6 expression by NonO-deficiency and PRDM1-deficiency were observed." (PMID 32765503, 2020).
neuroblastoma (3 papers, 2018 to 2025). Neuroblastoma (NB) is the most common solid, extracranial childhood tumor. "Beyond the observations made in neuroblastoma, NonO, through its association with SFPQ and other factors, may warrant consideration as a transcriptional supermediator." (PMID 38248868, 2024). "In neuroblastoma, NONO binds to lncUSMycN, a lncRNA transcribed from approximately 14 kb upstream of MYCN TSS, to post-transcriptionally up-regulate the MYCN expression." (PMID 29773901, 2018). "Recently, Zhang and colleagues proposed a model for the regulatory role of NonO in neuroblastoma." (PMID 38248868, 2024). "We find it interesting that the supermediator activity of NonO may function in neuroblastoma via its interaction and coregulation of BRD4/Bromodomain, which retards neuroblastoma growth via apoptosis." (PMID 38248868, 2024).
prostate carcinoma (3 papers, 2016 to 2024). A carcinoma that arises from epithelial cells of the prostate gland. "For example, NonO upregulation can lead to malignant breast cell proliferation, whereas NonO and SFPQ together promote castration-resistant prostate cancer progression." (PMID 38248868, 2024).
bladder cancer (2 papers, 2021). "It was recently published that another splicing factor, NONO, regulates the switch between FL- and S-SETMAR mRNA, as high amounts of NONO promote exon-2 inclusion and the accumulation of FL-SETMAR mRNAs in bladder cancer." (PMID 35047379, 2021).
colon adenocarcinoma (2 papers, 2011 to 2023). "Moreover, YBX1 could induce oxaliplatin resistance in colon adenocarcinoma cell lines by induction of NONO and RALY proteins." (PMID 35861369, 2023). "The depletion of only two proteins, NONO and RALY, lead to a greater sensitivity to oxaliplatin in both colon adenocarcinoma cell lines with at least two siRNA sequence molecules." (PMID 22118625, 2011).
developmental delay (2 papers, 2021 to 2022). "Additionally, ARFGEF2, MIPEP, NONO, SH2B1, and TMEM70 led to LVNC complicating developmental delay." (PMID 34819141, 2021).
HIV-1 infection (2 papers, 2020 to 2022). The type species of lentivirus and the etiologic agent of acquired immunodeficiency syndrome (AIDS). "However, during HIV-1 infection NONO (Non-POU Domain Containing Octamer Binding) protein binds to its capsid and activates cGAS signaling along with inducing cGAS association with the HIV DNA in the nucleus." (PMID 33643304, 2020).
intellectual disability syndrome (2 papers, 2021 to 2023). "NonO, which forms heterodimers with SFPQ, is associated with an intellectual disability syndrome, including macrocephaly and a thickened corpus callosum." (PMID 36674445, 2023).
ovarian carcinoma (2 papers, 2020 to 2025). A malignant neoplasm originating from the surface ovarian epithelium. "Mechanistic studies revealed that circMETTL6 inhibits ovarian cancer progression by recruiting the NONO protein, disrupting its interaction with POLR2A, and subsequently suppressing GDF15 transcription." (PMID 39899667, 2025).
triple-negative breast carcinoma (2 papers, 2022 to 2024). An invasive breast carcinoma which is negative for expression of estrogen receptor (ER), progesterone receptor (PR), and human epidermal growth factor receptor 2 (HER2). "Additionally, NONO, another RNA binding protein, is found to bind to STAT3 mRNA, increasing its levels in triple-negative breast cancer." (PMID 38164170, 2024).
abdominal aortic aneurysm (1 paper, 2019). Enlargement and ballooning of the vessel that supplies arterial blood to the abdomen, pelvis and legs. "The role of Non‐POU‐domain‐containing octamer‐binding protein (NONO) in the formation and development of angiotensin II (Ang II)‐induced abdominal aortic aneurysm (AAA) in apolipoprotein E‐knockout (ApoE−/−) mice is still unknown." (PMID 31512366, 2019).
amyotrophic lateral sclerosis (1 paper, 2018). Amyotrophic lateral sclerosis (ALS) is a neurodegenerative disease characterized by progressive muscular paralysis reflecting degeneration of motor neurons in the primary motor cortex, corticospinal tracts, brainstem and spinal cord. "These include TDP43, FUS, hnRNPA1, PSF/SFPQ and p54/NONO, all of which have been linked to neurodegeneration associated with amyotrophic lateral sclerosis and frontotemporal dementia." (PMID 29426953, 2018).
autism (1 paper, 2021). Persistent deficits in social interaction and communication and interaction as well as a markedly restricted repertoire of activity and interest as well as repetitive patterns of behavior. "RFX transcription factors bind to a X-box consensus motif, which was found by the authors in some neuronal specific enhancers and/or promoters of autism risk genes (such as AP2S1, KDM6B, ANK2, NONO, and MYT1L)." (PMID 34768579, 2021).
colorectal cancer (1 paper, 2025). A primary or metastatic malignant neoplasm that affects the colon or rectum. "We found that NCOR1, NONO, and PPP1CC were more highly expressed in right-sided colorectal cancer, while CLDN4, EGR1, and ID2 were more highly expressed in left-sided colorectal cancer." (PMID 41174721, 2025).